IL15RA (interleukin 15 receptor subunit alpha)
Description:
High-affinity receptor for interleukin-15. Can signal both in cis and trans where IL15R from one subset of cells presents IL15 to neighboring IL2RG-expressing cells (By similarity). In neutrophils, binds and activates kinase SYK in response to IL15 stimulation. In neutrophils, required for IL15-induced phagocytosis in a SYK-dependent manner. Expression of different isoforms may alter or interfere with signal transduction. [Isoform 5]: Does not bind IL15. [Isoform 6]: Does not bind IL15. [Isoform 7]: Does not bind IL15. [Isoform 8]: Does not bind IL15.
Synonyms: IL-15RA; CD215
Tractability: Antibody: UniProt places it where antibodies can reach, with high confidence; its Gene Ontology location is reachable by antibodies, with high confidence; UniProt predicts a signal peptide or a membrane-spanning region; the Human Protein Atlas places it where antibodies can reach. PROTAC: a small molecule that binds it is known. Other modalities: a drug acting on it is in phase 2 or 3 trials.
Gene: Protein-coding gene on chromosome 10 (5,943,639 to 5,978,187, reverse strand). Ensembl gene ENSG00000134470.
Subcellular location: Membrane; Nucleus membrane; Cell surface; Endoplasmic reticulum membrane (Isoform 5); Golgi apparatus membrane; Cytoplasmic vesicle membrane; Endoplasmic reticulum membrane (Isoform 6); Endoplasmic reticulum membrane (Isoform 7); Endoplasmic reticulum membrane (Isoform 8); Secreted, extracellular space (Soluble interleukin-15 receptor subunit alpha)
Subcellular location (Human Protein Atlas): Plasma membrane; Vesicles; Cytosol; Predicted to be secreted
Pathways (Reactome):
Immune System: Interleukin-15 signaling
Gene Ontology:
Molecular function: interleukin-15 receptor activity; protein binding; protein kinase binding; cytokine receptor activity
Biological process: interleukin-15-mediated signaling pathway; positive regulation of phagocytosis; cell surface receptor signaling pathway via JAK-STAT; negative regulation of apoptotic process; positive regulation of MAPK cascade; negative regulation of neuron projection development; response to nutrient levels
Cellular component: cell surface; interleukin-15 receptor complex; membrane; nuclear membrane; plasma membrane; endosome; cytoplasmic vesicle; cytoplasmic vesicle membrane; endoplasmic reticulum membrane; extracellular region; Golgi membrane
Genetic constraint (gnomAD): Loss-of-function variants: 22 observed, 21.51 expected, observed/expected ratio (o/e) 1.02, 90% interval 0.73 to 1.46. The upper end of that interval is the gene's LOEUF score, 1.46, which puts it in group 6 of 6, group 1 being the genes least tolerant of losing a copy. Missense variants: 339 observed, 332.78 expected, observed/expected ratio (o/e) 1.02, 90% interval 0.93 to 1.12. Synonymous variants: 161 observed, 140.2 expected, observed/expected ratio (o/e) 1.15, 90% interval 1.01 to 1.31.
Homologues: Orthologues: chimpanzee IL15RA (97% identical), macaque IL15RA (81% identical), guinea pig IL15RA (60% identical), dog IL15RA (55% identical), rat Il15ra (54% identical), mouse Il15ra (52% identical), zebrafish il15ra (23% identical).
Diseases named in the same sentence as IL15RA in open-access papers:
IL15RA is named in the same sentence as 111 diseases in open-access papers, as found by Europe PMC text mining. Sharing a sentence is not in itself a finding about the gene and the disease. The quoted sentences say what the papers report.
melanoma (18 papers, 2009 to 2026). A malignant, usually aggressive tumor composed of atypical, neoplastic melanocytes. "Proteomic profiling of melanoma cell lines stimulated with soluble IL-15Rα (sIL-15Rα) uncovered distinct, stage-specific responses." (PMID 42064067, 2026). "As tmbIL-15 is capable of reverse signaling upon IL-15Rα engagement, we investigated how this signaling axis modulates melanoma cell behavior across tumor stages." (PMID 42064067, 2026). "Intranasal administration of Neospora caninum modified to produce human IL-15 fused with IL-15Rα shows promise in treating lung metastases from melanoma." (PMID 40636453, 2025). "The expression of IL-15/IL-15Rα complexes by melanoma cells was evaluated both ex vivo and in vitro by tissue microarray, PCR, and flow cytometry." (PMID 37334356, 2023). "In this in vitro study, we demonstrated that genetically delivered IL-15/IL-15Rα modulates the composition and activation of melanoma surrounding immune cells and elicits immune cell-mediated anti-tumor immune responses." (PMID 37923822, 2023). "The aim of this study is to investigate the possible role of Interleukin-15/Interleukin-15 Receptor α (IL-15/IL-15Rα) complexes in melanoma development." (PMID 37334356, 2023). "Membrane-bound and secreted IL-15/IL-15Rα complexes are continuously present during progression in melanoma." (PMID 37334356, 2023). "Second, we analyzed the expression of the two IL-15Rα isoforms on the remaining melanoma cell lines." (PMID 37334356, 2023). "This study reports the use of the BacMam system to deliver and express self-assembling IL-15 and IL-15Rα genes to murine B16F10 melanoma and CT26 colon cancer cells." (PMID 34439192, 2021). "For example, IL-15 can also induce the expansion of NK and CD8+ T cell populations and thereby suppress the growth of malignant melanoma, and a complex of IL-15 and soluble IL-15Rα has even more potent effects." (PMID 26772545, 2016). "However, the impact of sIL-15/IL-15Rα complexes on melanoma progression, and their roles in the development of an immunosuppressive tumor microenvironment (TME) and the establishment of NK and T-cell exhaustion, have yet to be clarified." (PMID 37334356, 2023). "Here we found that K2-Fc, an antibody derivative that blocks the PD-1:PD-L1 axis and enables enhanced ADCC, could augment IL-15/IL-15Rα-mediated melanoma cell killing and could synergistically improve CD8+ T cell and NK cell activation." (PMID 37923822, 2023). "In conclusion, melanoma appears to display complex mechanisms of immune activation and regulation that have not been completely clarified, and in which, for instance, the possible role of IL-15/IL-15Rα complex and isoforms has been underestimated." (PMID 37334356, 2023). "Finally, by analyzing public datasets, we studied the correlation between IL-15 and IL-15Rα expressions and melanoma stage, NK and T-cell markers, and overall survival (OS)." (PMID 37334356, 2023). "IL-15Rα also mediates the anti-tumor effect of IL-15 in a B16 melanoma mouse model." (PMID 26993600, 2016). "In melanoma models it was demonstrated that stimulation of effector cells with IL-15/IL-15Rα complexes or the IL-15 fusion protein RLI (composed of the N-terminal domain of IL-15Rα coupled via a linker to IL-15) significantly reduced tumor burden." (PMID 27821119, 2016). "Since in melanoma patients’ high monomeric IL-15 serum levels have been reported to correlate with a poor clinical outcome, we asked what could be the consequences of a too-high and constant production of the IL-15/IL-15Rα complex." (PMID 37334356, 2023). "Indeed, in pre-clinical melanoma models, the presence in melanoma cells and/or stromal cells of the IL-15/IL-15Rα complex (either in membrane-bound or soluble form), or treatment with IL-15clpx, may lead to the inhibition of tumor progression and reduction of the lung and liver metastases." (PMID 37334356, 2023).
melanoma (continued). "Multi-step growth curves showed that murine melanoma (B16-F10 and B16.SIY) cell lines were permissive to vMyx-IL15Rα-tdTr infection." (PMID 25329832, 2014). "Since IL-15 is produced by a vast diversity of cells in vivo, we can postulate that endogenous IL-15 is presented by IL-15Rα harbored by Dex leading to significant NK cell proliferation in vivo after Dex vaccination and NKG2D restoration in melanoma patients." (PMID 19319200, 2009). "The nuclear localization of IL-15, similar to that reported in MELREO melanoma cells, is probably mediated by its specific receptor IL-15Rα, as IL-15 does not appear to be able to enter the nucleus by itself." (PMID 23950892, 2013). "In contrast, tumor-derived exosomes (Tex) harvested in the supernatants of melanoma cell lines did not bear IL-15Rα molecules." (PMID 19319200, 2009). "Primary melanoma cells predominantly express the non-cleavable transmembrane form (tmbIL-15), while metastatic cells also express a cleavable membrane-bound form (mbIL-15) complexed with IL-15Rα." (PMID 42064067, 2026).
breast carcinoma (10 papers, 2020 to 2025). "IL15RA encodes the interleukin 15 cytokine receptor, and knockdown experiments have confirmed that the protein plays a role in cell growth and apoptosis in breast cancer cell types." (PMID 37428809, 2023). "In contrast, the receptors for IL7 (IL7R) and IL15 (IL15RA) were significantly overexpressed in basal B compared to luminal breast cancer cells." (PMID 38055067, 2023). "In breast cancer, the hypermethylation of IL15RA gene promoter induced the upregulation of genes involved in adhesion and ECM-interaction pathways correlating with the OS of patients." (PMID 35359376, 2022). "Intratumoral GET with plasmid IL-15/IL-15Rα leads to a long-term survival benefit in 4T1 mammary carcinoma model." (PMID 33628206, 2020). "Antitumor activity of IL-15 was evaluated in two murine breast cancer models, mouse Her2/neu+ and 4T1-luc mammary cancers treated with systemic administration and intratumor delivery of plasmid IL-15/IL-15Rα, respectively." (PMID 33628206, 2020). "In addition, the cytotoxic effects of cytokine-based NIR-PIT in human cancer were evaluated in human breast cancer MDA-MB-231 cells with reportedly high levels of IL15Rα." (PMID 40886193, 2025). "Furthermore, IL15RA and IL2RA are predicted to be targeted by several breast-cancer associated SNPs in cd19 and cd4 primary cells, as well as in vHMEC." (PMID 37428809, 2023). "Moreover, IL15Rα + TAMs, which express high levels of IL-15Rα, not only reduce CX3C chemokine ligand 1 levels in tumor cells but also inhibit CD8 + T-cell recruitment through the IL-15/IL-15Rα complex, contributing to poorer survival outcomes in breast cancer patients." (PMID 39068459, 2024). "Studies have reported that the coexpression of IL15RA and IL15 in breast cancer cell lines can promote cancer proliferation, prevent cell apoptosis, and enhance cell migration." (PMID 35693827, 2022). "Studies have reported that the coexpression of IL15RA and IL15 in breast cancer cell lines can promote tumor cancer proliferation, prevent tumor cell apoptosis, and enhance cell migration." (PMID 35693827, 2022). "The goal of this study was to examine the activity of IL-15/IL-15Rα complex (IL-15cx) to CD8+ T cells and evaluate its potential efficacy in murine breast cancer models." (PMID 33628206, 2020). "However, in a mouse model of breast cancer, IL-15Rα+TAM releases IL-15Rc (the IL-15/IL-15Rα complex) to reduce the expression of chemokine CX3CL1 in tumor cells, thereby reducing recruitment to CD8+T cells." (PMID 38279145, 2024).
glioma (8 papers, 2013 to 2024). A benign or malignant brain and spinal cord tumor that arises from glial cells (astrocytes, oligodendrocytes, ependymal cells). "The role of IL-15 in modulating the effect of EE was also confirmed with glioma Il15ra–/– mice: in these animals, we observed increased tumor size in SE, and a smaller effect of reducing tumor size in EE." (PMID 29286001, 2017). "vMyx-IL15Rα-tdTr and vMyx-tdTr showed a different growth phenotype in the glioma cell line (GL261) and produced lower viral titers." (PMID 25329832, 2014). "J100D produces soluble mIL-15/IL-15Rα complex following infection of murine neuroblastoma and murine glioma cell lines with variable permissiveness to oHSV replication and killing." (PMID 24312353, 2013). "As soluble mIL-15/IL-15Rα was detected from murine neuroblastoma (Neuro-2a) and glioma (GL261, CT-2A) cell lines following J100D infection, this virus can be utilized to study the combined effects of oHSV and mIL-15/IL-15Rα in multiple tumor models." (PMID 24312353, 2013). "In vivo, oncolytic HSV-1 OV-IL15C, expressing human IL-15 and its receptor IL-15Rα, were demonstrated to have significant suppression of tumor growth and prolonged survival in glioma-bearing mice compared to a therapy using the same OV without IL-15/IL-15Rα gene insertion." (PMID 38396720, 2024). "A modification of this virus expressing IL15Rα (vvDD-IL15Rα), aimed at boosting the immunostimulating effect of the virus in combination with the direct lytic effect, has been proven to be quite efficient in killing murine glioma cells in vitro." (PMID 33066689, 2020). "The soluble mIL-15/IL-15Rα complex is bioactive, as demonstrated by its ability to stimulate enriched murine splenic NK cells to survive and proliferate in culture as well as reduce the viability of syngeneic glioma cells." (PMID 24312353, 2013). "In immunocompetent animal models of glioma, MYXV armed with IL15Rα-247 has been shown to be a safe and powerful agent against brain tumors when combined with other immunotherapeutic methods." (PMID 34675919, 2021).
glioblastoma (6 papers, 2015 to 2025). The most malignant astrocytic tumor (WHO grade IV). "For instance, anti-EFGR CAR-NK cells synergized with oncolytic virus expressing IL-15/IL15Rα sushi domain fusion protein enhanced the persistence and infiltration of CAR-NK cells and suppressed the growth of glioblastoma in vitro and in vivo." (PMID 38726000, 2024). "produced OV-IL15C, a herpes simplex 1-based human IL15/IL15Rα sushi domain fusion protein, as well as commercial EGFR-CAR NK cells, and examined their efficiency as a monotherapy and in combination in vitro and several glioblastoma (GBM) mice models." (PMID 36703982, 2022). "The researchers engineered a fusion protein combining IL-15 and IL-15Rα (designated OV-IL15C), which was expressed within gliomas and demonstrated the ability to enhance cytotoxicity against glioblastoma (GBM) both in vivo and in vitro, while also improving the survival of NK and CD8+ T cells." (PMID 39055561, 2024).
pancreatic cancer (6 papers, 2015 to 2025). "In this study, we explored the activity of NKG2D-CAR T expressing IL-15/IL-15Rα complex (IL15C) on pancreatic cancer." (PMID 40625735, 2025). "In a pancreatic cancer (PC) model, aerobic exercise activated the IL-15/IL-15Rα axis to drive CD8+ T cell infiltration, with similar immune responses observed in clinical samples." (PMID 40699773, 2025). "Our results revealed that activated PSCs secrete IL15, which upregulates the expression of IL15RA in pancreatic cancer cells via a paracrine signaling pathway." (PMID 39396119, 2024). "The study using a pancreatic cancer model suggested that aerobic exercise restricts pancreatic tumor growth by enhancing anti-tumor immunity, driven by IL-15Rα+ CD8 T cells." (PMID 36230785, 2022). "identifies an important role for exercise in driving an immune-mediated anti-tumor effect in pancreatic cancer through the activation of the IL-15/IL-15Rα axis." (PMID 36225922, 2022). "The data of this study showed that secreted IL-15/IL-15Rα complex could enhance the cytotoxic effect of NKG2D-CAR T cells on pancreatic cancer cell lines and could also promote the proliferation and survival of T cells, especially CD8+ T cells." (PMID 40625735, 2025). "IL15RA on the surface of pancreatic cancer cells is upregulated after coculture." (PMID 39396119, 2024). "To further analyze whether STAT3 can be activated by IL15RA, we used small interfering RNA to silenceIL15RA in pancreatic cancer cells." (PMID 39396119, 2024). "Furthermore, we used small interfering RNA to silenceIL15 in activated PSCs and detected whether it affects the protein level of pancreatic cancer cells.IL15 silencing decreased IL15RA, p-STAT3, GPX4 and ACSL3 expression levels." (PMID 39396119, 2024). "The upregulated levels of IL15RA, ACSL3 and GPX4 in pancreatic cancer cells were verified by qRT-PCR and western blot analysis." (PMID 39396119, 2024). "Pathway analysis of its target genes via DAVID showed enrichment (FDR < 5 %) of genes in the Jak-Stat signaling pathway, including several receptors of interleukins (PTPN6, IL22RA1, CREBBP, IL28RA, IL15RA, PIK3R5, STAT3) and pancreatic cancer pathways (VEGFC, ACVR1B, PIK3R5, EGF, STAT3)." (PMID 26572553, 2015).
asthma (5 papers, 2012 to 2025). "IL15RA has been found to be overexpressed in patients with asthma, albeit only with a moderate correlation to eosinophil count." (PMID 35935937, 2022). "IL15 expression also positively correlated with IL15RA expression in patients with asthma, which could represent trans presentation of IL-15 by damaged airway cells." (PMID 40048261, 2025). "For example, lung epithelial cells constitutively express IL-15 and IL-15Rα, and neutrophils and macrophages can be a major source of IL-15 that is produced during a variety of lung inflammatory diseases including sarcoidosis, tuberculosis, bronchitis, and asthma." (PMID 22624047, 2012).
colon cancer (5 papers, 2012 to 2025). "After 27 days of the first treatment, plant-produced Pembrolizumab-IL-15Rα-IL-15 significantly inhibited colon cancer growth with an average final tumor volume of 103.11 ± 85.68 mm3." (PMID 39808627, 2025). "We previously showed that IL-15:IL15Rα-secreting cell-based cancer vaccine surpassed those expressing IL-15 alone for eliminating tumors, preventing tumor recurrence and enhancing overall survival of tumor-bearing mice in CT26 colon cancer cells." (PMID 34439192, 2021).
Obesity (5 papers, 2016 to 2021). Accumulation of substantial excess body fat. "Our observations complement another recent study that showed that IL-15Rα deficient mice are protected from obesity." (PMID 27684068, 2016). "To investigate whether the deletion of OGT and IL-15rα could negates the mKO protection against metabolic perturbations associated with obesity, we fed mice with a HFD." (PMID 34326778, 2021). "We and others have shown that ablation of IL15RA in mice increases spontaneous activity, exercise capacity and protects against diet-induced obesity." (PMID 31849697, 2019). "Together with our previously published work on exercise capacity and resistance to diet-induced obesity, these findings strengthen the rationale for the future development of new pharmacological exercise mimetic strategies by blocking IL15RA." (PMID 31849697, 2019). "CNTNAP2, GLI2, DPT (dermatopontin), AEBP1, ITIH5, CXCL11, GDNF (glial cell derived neurotrophic factor), MCHR1, FLT3, ELANE (elastase, neutrophil expressed), OSMR (oncostatin M receptor) and IL15RA are involved in development of obesity, but these genes might be key for progression of HF." (PMID 34218797, 2021). "Lack of interleukin 15 receptor alpha (IL15RA) increases spontaneous activity, exercise capacity and protects from diet-induced obesity by enhancing muscle energy metabolism, suggesting a role as exercise mimetic for IL15RA antagonists." (PMID 31849697, 2019).